MSLN (mesothelin)
Diseases named in the same sentence as MSLN in open-access papers (continued):
Sharing a sentence is not in itself a finding about the gene and the disease.
tumor (continued). "The average tumor weight in the anti-MSLN CAR-like NK group was 0.29 g, which was significantly lower than that in the PBS group (1.07 g) and the NK + MSLN×CD16A group (0.64 g)." (PMID 41436559, 2025). "Mesothelin (MSLN) is a tumor biomarker expressed at highlevelson the surface of numerous cancers with extremely limited expressionin healthy tissues." (PMID 41143950, 2025). "Studies have shown that targeting FOLR1 or MSLN individually results in a 48-76% likelihood of near-complete tumor elimination, while simultaneous targeting of both proteins increases tumor cell killing to 88% in ovarian cancer." (PMID 40092990, 2025). "Our results in the murine tumor model demonstrated that combination therapy exhibited the greatest antitumor effects and prolonged survival compared to control, MSLN-CAR T cells, and HSV-MSLN monotherapies." (PMID 40366419, 2025). "The scFvs against different tumor-associated antigens including HER2 (H) and mesothelin (M) were used to construct a series of second-generation CARs." (PMID 39809749, 2025). "In111-K1 predominantly accumulated in MSLN-positive tumor masses, highlighting the potential of MSLN as a tumor-specific marker." (PMID 41335396, 2025). "Single-cell transcriptomic analysis revealed that transforming growth factor–β (TGF-β)–producing tumor cells up-regulated major histocompatibility complex molecules and down-regulated MSLN post–CAR-IL-15 iNK treatment." (PMID 40315330, 2025). "The MSLN/CD3 bsAb significantly inhibited the tumor growth of H9 cells in the presence of NKT, and this effect was independent of the dose." (PMID 39995672, 2025). "While less dramatic than the changes seen with CA125 or Mesothelin, reduced Enolase 2 expression reflects an impact on tumor metabolism, essential for cancer cell survival, proliferation, and adaptation to therapy." (PMID 41515404, 2025). "This modification endows anti-MSLN uCAR-like NK cells with both targeting and tumor tissue penetration capabilities." (PMID 41436559, 2025). "In vivo, HSV-MSLN delivered MSLN on the tumor cell surface and reprogrammed the TME toward an immunogenic state." (PMID 40366419, 2025). "MSLN has been extensively studied across multiple tumor types, with its expression patterns and prognostic value varying according to tumor type." (PMID 41400642, 2025). "In the presence of MSLN-positive tumor cells (HGC27, MKN45, and NCI-N87), CIML NK cells cocultured with MSLN×CD16A presented significantly increased levels of degranulation, as assessed by CD107a expression." (PMID 41436559, 2025). "The MSLN/CD3 bsAb significantly inhibited the tumor growth of H9 cells in the presence of γδT, and this effect was dose-dependent." (PMID 39995672, 2025). "In this study, we investigated treosulfan and fludarabine anti-tumor efficacy against ovarian cell lines, impact of MSLN expression and hypoxia, and effect on MSLN-CAR T cells." (PMID 38954005, 2024). "Across the entire cohort, MSLN low expression had a significant association with higher tumor mutation burden (TMB) and DNA mismatch repair (dMMR)/microsatellite instability-high (MSI-H) positivity in comparison to MSLN high expression." (PMID 39174744, 2024). "In order to evaluate the in vivo anti-tumor activity of MSLN-CAR T cells, we established a xenograft ovarian cancer tumor model through intraperitoneal injection of OVCAR3 cells into NCG mice." (PMID 38637885, 2024). "Using a VHH that binds both human and mouse MSLN, we demonstrate the occurrence of fatal off-tumor toxicity of high-affinity MSLN CAR T cells in a mouse model." (PMID 39576012, 2024). "On the way to overcome the challenge of tumor heterogeneity, some researchers explored the effect of tumor heterogeneity on the function of MSLN-CAR-T (Mesothelin, MSLN) cells and searched for strategies to overcome this effect." (PMID 38919533, 2024). "Examples of antigens comprising the tumor microenvironment that are active areas of investigation include mesothelin and Claudin18.2." (PMID 39519112, 2024).
tumor (continued). "Higher frequency of viable MSLN + K562 tumor cells was observed when co-incubated with MBBz CAR T cells previously exposed to GCs." (PMID 38475830, 2024). "The immunohistochemical staining revealed increased mesothelin expression in tumor cells (MSLN +++84%)." (PMID 38799440, 2024). "One strategy to overcome poor T cell tumor trafficking and persistence involved evaluating the intrapleural administration of mesothelin-targeted CAR T cells, followed by pembrolizumab." (PMID 38610930, 2024). "The authors do argue that in vivo efficacy was highly dependent on the heterogeneity of mesothelin expression, the number of cumulative hits per tumor cell and tumor doubling time." (PMID 39431018, 2024). "The typical structure consists of an ectodomain, containing a single-chain variable fragment (scFv) that binds to a specific tumor antigen (in this case, MSLN), a hinge, a transmembrane domain, and an endodomain with the signaling domains." (PMID 38893092, 2024). "The effectiveness of tumor-targeted anti-mesothelin chimeric antigen receptor (CAR)-T cells is enhanced by pre-conditioning the tumor microenvironment (TME) with folate receptor (FR)-specific CAR-T cells." (PMID 39338894, 2024). "Tumour tissue MSLN expression was 1.9-fold higher in OC versus 0.1 in benign tumours and 2.9 in high-grade versus 1.7 in low-grade OC." (PMID 38435431, 2024). "The size and the number of clones and tumor spheres were decreased in ASPC-1 with MSLN KO, and increased in Mia PaCa-2 with MSLN OE." (PMID 38628720, 2024). "As MSLN expression is rather low in most normal tissues, but highly elevated in tumors, the current main strategies for targeting MSLN include tumor vaccines, antibody-based therapies and chimeric antigen receptor T-cell (CAR-T) therapies." (PMID 38570866, 2024). "Future prospective analysis will be required to answer such important questions in addition to uncovering the similarities between CMS4 and MSLN high-expression tumor profiles." (PMID 39174744, 2024). "SEB #H22 and #H30‐amplified human PBMCs also demonstrated stronger T cell cytotoxicity in the presence of tumor‐targeted superantigen engager against mesothelin‐expressing HEK293T cells." (PMID 38937984, 2024). "In xenograft model, tumor volume was decreased (tumor grew slower) in MSLN KO group compared to control group, while increased in MSLN OE group." (PMID 38628720, 2024). "Collectively, MSLN CAR‐iNK cells show significantly enhanced cytotoxic activity against MSLN‐positive tumour cells." (PMID 39136096, 2024). "The image results showed that the distributions of VE-cadherin, JAM-A and claudin-5 became discontinuous and vastly diminished in hBMVEC monolayers treated with conditioned medium derived from tumor cells with relatively high expression of MSLN." (PMID 38570866, 2024). "Its overexpression in a wide range of solid cancers, combined with its low expression on normal mesothelial cells, makes MSLN an attractive tumor antigen for targeted cancer therapy, including T cell–based therapies." (PMID 39576012, 2024). "We found a markedly decreased number of mesothelin-positive tumor cells and an increase in tumor-infiltrating CAR-T cells in the miltefosine-treated group compared with the M28Z group." (PMID 39657666, 2024). "APC (p = 1.7e-20), BCL9 (p = 0.0006), CREBBP (p = 8.5e−5), FLCN (p = 1.39e−7), NSD2 (p = 0.002), and EP300 (p = 1.42e−6) all had significantly higher mutation rates in MSLN low expressing tumor samples compared to MSLN high expressing tumor samples." (PMID 39174744, 2024). "In our study, we have characterised the expression of the tumour differentiation antigen mesothelin in these cancer types and demonstrated the efficacy of the mesothelin‐targeted hYP218 CAR T cells in gastric and colorectal cell lines and tumour xenografts." (PMID 39548594, 2024). "Overall, tumor samples from metastatic sites expressed MSLN at significantly higher levels compared to the primary tumor site (q ≤ 0.01)." (PMID 39174744, 2024).
tumor (continued). "Our data suggests a higher proportion of MSLN positivity in paired/matched tumor tissue compared to normal tissue." (PMID 39174744, 2024). "Mesothelin (MSLN) is a molecule expressed on the surface of various solid malignant tumor cells that is suitable as a target of tumor cells with high MSLN expression for CAR-T-cell therapy." (PMID 39023820, 2024). "Studies have indicated a prevalence of MSLN expression in 34%–67% of TNBC samples, associating it with cancer cell proliferation and tumor progression." (PMID 39294656, 2024). "The interaction between MUC16 (CA125) and mesothelin is believed to facilitate tumor implantation and metastasis." (PMID 38637885, 2024). "ShengKai reported that mesothelin expression was significantly elevated in the serum and tumor tissue samples of patients with NSCLC who had BM." (PMID 39766230, 2024). "Clone formation and tumor sphere formation were decreased in MSLN low-expressing cells whereas increased in MSLN high-expressing cells." (PMID 38628720, 2024). "Immune cell response, relative ‘heat’ of the tumor microenvironment, immune/inflammatory pathway activations, and genetic mutation profiles may predict the likelihood of benefit from immunotherapy in relation to MSLN expression, specifically in patients with MSS tumors." (PMID 39174744, 2024). "Abnormal MSLN expression promotes tumor development by inducing tumor cell proliferation, anti-apoptosis and metastasis." (PMID 38570866, 2024). "Anetumab-ravtansine binds to mesothelin on tumor cells, cleaves the disulfide linker, and internalizes the drug to release DM4, followed by DM4 binding to tubulin, which prevents microtubule polymerization, and causes apoptosis subsequent cell cycle arrest." (PMID 39456611, 2024). "The effects of MSLN on cell phenotypes, expression of EMT-related markers, clone formation, tumor sphere formation, and pathologic role of MSLN in tumorigenesis were detected." (PMID 38628720, 2024). "In this study, we constructed CARs using mutant variants of a single-domain nanobody that bind both human and mouse MSLN with a wide range of affinities and examined tumor responses and their toxicities from on-target, off-tumor interactions in mouse models." (PMID 39576012, 2024). "We next evaluated CD28 and 4-1BB MSLN CAR T cells antitumor potency against K562 tumor cells expressing GFP and MSLN after 3 GC exposures (10 μg/ml Dx and 50 μg/ml MP) over a one-week period using a flow cytometry based killing assay." (PMID 38475830, 2024). "Taking this one step further, the top quartile of MSLN-expressing tumor cohorts exhibited significantly longer survival times, again supporting MSLN as a potential biomarker." (PMID 39174744, 2024). "Taken together, these data suggest that the effect of MSLN on tumor cell penetration of the BBB is dependent on MET." (PMID 38570866, 2024). "Tumor mesothelin expression levels correlate with progression-free survival (PFS) and overall survival (OS) by subgroup assessments, which are part of the ongoing analysis from this phase II investigation." (PMID 39456611, 2024). "In conclusion, these results show that the MSLN CAR‐iNK cells can efficiently suppress tumour development and prolong the survival of tumour‐bearing mice." (PMID 39136096, 2024). "MSLN expression was significantly elevated in both serum and tumor tissue samples from NSCLC patients with BM and correlated with a poor clinical prognosis." (PMID 38570866, 2024). "Mesothelin is a transmembrane antigen for tumor differentiation that exhibits significant expression in a variety of solid tumors, as determined by immunohistochemistry (IHC)." (PMID 39456611, 2024). "Since mesothelin is highly expressed in these tumour types, we evaluated the therapeutic benefits of anti‐mesothelin hYP218 CAR T cells alone, and in combination with anti‐PD1 antibody, pembrolizumab." (PMID 39548594, 2024).
tumor (continued). "MSLN, a cell surface glycoprotein, is highly expressed in various tumor tissues, while it is found at very low levels in normal human tissues." (PMID 38570866, 2024). "Consistently, an increase in cytokine production was observed in the supernatant of MT CAR-T cells and MSLN+ tumor cells." (PMID 37359558, 2023). "After dividing patients according to tumor MSLN expression, those with >21.05% positive cells/mm2 are grouped in the top curve and those with ≤21.05% positive cells/mm2 are at the bottom curve." (PMID 37901248, 2023). "When administered with LD chemotherapy and IL-2, mesothelin CAR-T cells have been associated with progressive disease (PD) in 14/15 patients with mesothelin-positive tumours at 3.5 months (NCT01583686)." (PMID 37835509, 2023). "Compared with other groups, the combination of the low-dose anti-PD1 antibody with ACOD1-/- MSLN-CAR-iMACs had the most superior tumor suppression effect, and markedly lengthened the survival time." (PMID 37723178, 2023). "Studies have been carried out with and without lymphodepleting chemotherapy and have included other tumor types that express mesothelin, such as NSCLC, pancreatic and ovarian cancers as well as MPM." (PMID 37296902, 2023). "Mesothelin is a tumour differentiation antigen present on pleural, peritoneal and pericardial mesothelial cells." (PMID 37238197, 2023). "One group showed an improved overall survival in tumours diffusely positive for MSLN staining compared to MSLN‐negative/partial staining tumours." (PMID 37040900, 2023). "Similar to T cell engagers, NK cell engagers are in development in the preclinical space, using either mesothelin or B7-H3 as the tumor target." (PMID 37296902, 2023). "Another potential target for CAR molecule development is Mesothelin, a tumor differentiation glycoprotein that is involved in cell adhesion, which is normally expressed on the mesothelial cells but is overexpressed in several solid neoplasms including TNBC." (PMID 36900394, 2023). "Its anti-PDAC effects were partially mediated by Mesothelin (MSLN), another highly expressed tumor-associated antigen in PDAC." (PMID 37894284, 2023). "In summary, these results indicated that anti-α-TIGIT enhanced the sustained killing effect of anti-MSLN CAR-T cells on tumor cells." (PMID 37359558, 2023). "To evaluate the anti-tumor activity of ACOD1-/- MSLN-CAR-iMACs in vivo, we used two different xenograft solid tumor models with the NOD/SCID/IL2rγnull (NSG) mice." (PMID 37723178, 2023). "The anti-MSLN CAR-T cells showed signs of tumor recurrence in the late stage of the experiment, while the MT CAR-T cells and anti-MSLN CAR-T ± anti-α-TIGIT mice showed no tumor recurrence." (PMID 37359558, 2023). "Low MSLN expression by tumor cells was detected in 20.3% of women and 32.9% of men, whereas high expression of MSLN by tumor cells was present in 39.2% of men and 7.6% of women (P = 0.04)." (PMID 37901248, 2023). "We demonstrated for the first time the use of an anti-MSLN nanobody as PET radiotracer for same day imaging of MSLN+ tumours, targeting an epitope compatible with the monitoring of amatuximab-based therapies and current SS1-derived-drug conjugates." (PMID 37388728, 2023). "Although the precise mechanisms have yet to be fully understood, current evidence suggests potential implications for mesothelin in tumor cell adhesion, progression, proliferation, survival, and resistance to chemotherapy." (PMID 37020537, 2023). "Of note, only patients with Mesothelin membrane staining observed in >50% of tumour cells were included in the study." (PMID 37761312, 2023). "According to the median expression of MSLN, 21.05% of tumor cells were positive (interquartile range, 5.61–38.68% positive cells)." (PMID 37901248, 2023). "Mesothelin, a 40 kDa protein, is highly expressed in tumor tissues of patients with serous or endometrioid EOC." (PMID 37244991, 2023).
tumor (continued). "Overexpression of MSLN results in increased proliferation, migration, and invasion in vitro and increased tumor growth and progression in vivo, as well as in a marked reduction in endogenous miR-198 levels." (PMID 37631252, 2023). "These researchers reported that an OR gate CAR-T platform based on CA125 and mesothelin would be the most applicable choice as a high percentage of malignant cells in around 60% of the assessed tumor samples were proficient in the expression of either antigen." (PMID 38146364, 2023). "Together these data suggest TriKE can enhance anti-tumor activities of healthy NK cells against a range of NSCLC subtypes expressing mesothelin." (PMID 36911670, 2023). "Anti-MSLN CCR2b CAR and anti-MSLN CCR4 CAR-T cells have increased migration rates into tumor supernatants expressing high levels of MCP-1 in vitro." (PMID 36900151, 2023). "The CD3ζ and CD28 signaling domains were established in two separate CAR and T lymphocyte lines and they simultaneously targeted tumor cells containing the antigens mesothelin and FRα." (PMID 37457288, 2023). "At the protein level, they verified that when MUC1 and MSLN were labeled separately and simultaneously, the percentage of tumor cells with a high labeling pattern (2+ or 3+) increased from 56% and 62% to 82%." (PMID 36900151, 2023). "We demonstrated that ATTO-647N- and 68Ga-conjugated S1 can specifically target MSLN-positive tumours in vivo, highlighting its potential for non-invasive imaging of MSLN as a companion test for MSLN-targeting therapies." (PMID 37388728, 2023). "Solid malignancies, such as ovarian, pancreatic, and mesothelioma tumors, express mesothelin, a transmembrane tumor antigenic substance, strongly." (PMID 37469419, 2023). "Compared with the untreated or the MSLN-CAR-iMACs treated mice, treatment with ACOD1-/- MSLN-CAR-iMACs led to significant inhibition of tumor growth." (PMID 37723178, 2023). "Blocking the localization of PKA to the immune synapse increased the migration of anti-MSLN CAR-T cells to the tumor and enhanced the antitumor effect in a mouse model of melanoma." (PMID 36900151, 2023). "Only one study has analysed MSLN expression by IHC and controlled for other confounders including tumour subtype in a multivariate analysis." (PMID 37040900, 2023). "Intravenous administration of third-generation CAR-T cells that target mesothelin as a therapy for gastric cancer and PC led to regression of the tumor and even elimination in a mouse model." (PMID 37190310, 2023). "By modifying the bacterial vectors to express cytokines and tumor antigens (TAs), such as IL-2 or mesothelin, they can induce targeted immune responses from T and NK cells that specifically recognize tumor cells." (PMID 37681891, 2023). "Here, we found that overexpression of MSLN plays an important role in the progression from HGIL to ISL within the same tumor." (PMID 35920319, 2023). "On the one hand, tumour-associated antigens, such as human epidermal growth factor receptor 2 (HER2) or mesothelin, are often also expressed in healthy tissues, leading to on-target off-tumour toxicities." (PMID 37291434, 2023). "In summation, the existing dataset lends support to the notion of extracellular PSCA exerting anti-tumor actions, conceivably facilitated through interactions with MSLN." (PMID 37894284, 2023). "Further studies have shown that MSLN promotes tumor cell survival and proliferation through NF-κB pathway activation, resulting in an increase of interleukin-6 level." (PMID 37901248, 2023). "Few tumor antigens are under investigation, such as Mesothelin (MSLN) for CAR-T cell therapy and Wilms Tumor antigen (WT1) for therapeutic cancer vaccines." (PMID 37923723, 2023). "CA125, mesothelin, and FRα had the highest to lowest expression rates, respectively, in tumor samples and percentages of malignant cells at the protein level." (PMID 38146364, 2023).